EFNB1 (ephrin B1)
Diseases named in the same sentence as EFNB1 in open-access papers (continued):
Sharing a sentence is not in itself a finding about the gene and the disease.
gastric cancer (3 papers, 2003 to 2021). A primary or metastatic malignant neoplasm involving the stomach. "In pancreatic and gastric cancer, Ephrin-B1 induces the secretion of MMP8 and is later cleaved by MMP8 as a feedback loop." (PMID 34059618, 2021). "Since hek5 is also upregulated in gastric cancer cells following RA treatment, we are now investigating the expression of ephrin-B1 and hek5 in detail to determine their functions in human gastric cancer cell growth and in RA-mediated cell growth inhibition." (PMID 12671705, 2003). "However, MMP8 activity can also be harmful, as shown for pancreatic and gastric cancers, in which the interaction between MMP8 and Ephrin-B1 seems crucial, and hepatocellular carcinoma, where MMP8 was shown to activate the PI3K/Akt/Rac1 pathway." (PMID 31514474, 2019).
Hypertelorism (3 papers, 2011 to 2025). Interpupillary distance more than 2 SD above the mean (alternatively, the appearance of an increased interpupillary distance or widely spaced eyes). "The mechanisms by which loss of function of EFNB1 or imbalance in EFNB1 expression lead to a consistent phenotype of hypertelorism remain unclear." (PMID 21542058, 2011). "Interestingly, duplications of the EFNB1 region have been previously reported in patients with hypertelorism, and it has been shown that the X chromosome bearing the EFNB1 duplication produces more EFNB1 transcript than the normal X chromosome." (PMID 40490530, 2025).
injury (3 papers, 2015 to 2024). Damage inflicted on the body as the direct or indirect result of an external force, with or without disruption of structural continuity. "We previously observed that astrocytes express ephrin-B1, and that ephrin-B1 in astrocytes regulates both excitatory and inhibitory synapse development in the CA1 hippocampus and astrocyte immunoreactivity following traumatic brain injury." (PMID 39437409, 2024).
leukemia (3 papers, 2016 to 2024). A malignant (clonal) hematologic disorder, involving hematopoietic stem cells and characterized by the presence of primitive or atypical myeloid or lymphoid cells in the bone marrow and the blood. "EFNB1 was detected in leukaemia cell lines and bone marrow and was shown to be involved in normal haematopoietic development and tumorigenesis." (PMID 27434032, 2016). "Like CD34‐positive leukemia‐initiating AML cells we find ROBO4 significantly overexpressed in CD34‐positive ALL samples, but we also find other axonal growth guidance genes upregulated, such as EFNB1 and EPHA7." (PMID 35271751, 2022).
lymphoma (3 papers, 2018 to 2025). A malignant (clonal) proliferation of B- lymphocytes or T- lymphocytes which involves the lymph nodes, bone marrow and/or extranodal sites. "Our previous studies have illuminated the role of EFNB1 in fostering the malignant progression of lymphomas, alongside its close association with drug response, cellular origin, and prognosis in B-cell lymphomas." (PMID 39864628, 2025). "In human patients, lymphomas with low UTX expression also express high levels of Efnb1, and cause significantly poor survival." (PMID 30006524, 2018). "Previously, we had observed that overexpression of EFNB1 significantly enhanced the sensitivity of lymphoma cells to doxorubicin (DOX) and vincristine (VCR)." (PMID 39864628, 2025). "Within this coculture paradigm, featuring stromal cells (S) and B-lymphoma cells (B), wildtype EFNB1-RBD-Fc exhibited a notable inhibitory effect on cellular proliferation." (PMID 39864628, 2025). "A study revealed that EFNB1/2 can bind to IL7R in a cis-interaction manner in T-lymphoma cells, serving as an example of the cis-acting mechanism." (PMID 39864628, 2025). "Efnb1 cDNA was retrovirally introduced into Eμ-Myc;p19Arf−/− lymphoma cells, and Efnb1-expressing cells were injected into recipient mice to form lymphomas." (PMID 30006524, 2018). "Compared with lymphoma cells infected with vector control, which developed lymphoma mostly in lymph nodes, lymphoma cells expressing Efnb1 showed enhanced aggressiveness and a more disseminated distribution in mice." (PMID 30006524, 2018). "In half of the mice bearing the Efnb1-expressing lymphomas, we observed blood in abdomen cavities and visible blood vessels extending towards tumors." (PMID 30006524, 2018). "In addition, ectopic expression of Efnb1 in Eμ-Myc;p19Arf−/− lymphoma cells could also provide a tractable system to study brain metastasis of lymphomas, which is an important cause of death for lymphoma patients." (PMID 30006524, 2018). "All mice bearing Efnb1-expressing lymphomas showed blood infusion under skull, again suggestive of the aggressive nature of Efnb1-expressing lymphomas." (PMID 30006524, 2018). "Lastly, in 7 out of 9 mice injected with Efnb1-expressing Eμ-Myc;p19Arf−/− cells, huge lymphoma formed at kidneys, whereas only 1 out 9 in the control group showed such phenotype." (PMID 30006524, 2018). "In addition, all mice injected with Efnb1-expressing Eμ-Myc;p19Arf−/− cells showed skull bulges due to lymphoma infiltration, which is also frequently seen in Eμ-Myc;UTX-knockout mice." (PMID 30006524, 2018). "Next, we analyzed whether ectopic expression of Efnb1 enhances the aggressiveness of Eμ-Myc lymphoma cells in vivo." (PMID 30006524, 2018). "Importantly, we showed that UTX loss not only promotes tumor formation, it also strongly enhances the aggressiveness of lymphoma, as evidenced by brain dissemination and formation of blood vessels, through upregulation of Efnb1." (PMID 30006524, 2018). "Moreover, analysis of the human lymphoma dataset also showed that UTX-low lymphomas tend to express high levels of Efnb1." (PMID 30006524, 2018). "Among the highly overexpressed genes in UTX-knockout lymphomas, Efnb1 may contribute to the enhanced dissemination and blood vessel formation phenotype." (PMID 30006524, 2018). "Exploring the non-Eph cis-interacting proteins of EFNB1 under physiological conditions, including those within lymphoma cells themselves and stromal cells, will be an important research topic in the future." (PMID 39864628, 2025). "Taken together, these data showed that overexpressed Efnb1 could recapitulate the dissemination and blood vessel formation phenotype observed in UTX-knockout lymphomas." (PMID 30006524, 2018). "Through transcriptome analysis, we found Efnb1 is overexpressed in UTX-knockout tumor, and subsequent experiments demonstrated that Efnb1 overexpression in lymphoma cells indeed recapitulated the enhanced dissemination and blood vessel formation phenotypes in UTX-knockout mice." (PMID 30006524, 2018).
lymphoma (continued). "Although we have not yet identified the interacting proteins for EFNB1, based on the unique nonaggregating and suspension properties of lymphoma cells, along with the available experimental data, we have been able to gain insights into the specificity and complexity of the cis-interaction mode." (PMID 39864628, 2025).
pancreatic cancer (3 papers, 2010 to 2021). "The intracellular C-terminus of ephrin-B1, that is required for invasion of pancreatic cancer cells in vitro and in vivo in mice, was shown to regulate the release of MMP8 from these cells via activation of the cell trafficking regulator, Arf1." (PMID 31514474, 2019). "EphB2-ephrin-B1 induces the invasiveness of pancreatic cancer cells." (PMID 34360867, 2021).
rheumatoid arthritis (3 papers, 2017 to 2024). A chronic, systemic autoimmune disorder characterized by inflammation in the synovial membranes and articular surfaces. "Work in a rheumatoid arthritis model showed that ephrin B1 increased tumor necrosis factor alpha (TNFα) and interleukin-6 (IL-6) actions in lymphocytes." (PMID 38501146, 2024). "Previous study found that ephrin-B1 is highly expressed in peripheral blood lymphocytes (PBLs) derived from patients with rheumatoid arthritis (RA)." (PMID 28194092, 2017). "Others have also shown a role for ephrin B1 and TNFα in rheumatoid arthritis models." (PMID 38501146, 2024).
amyotrophic lateral sclerosis (2 papers, 2017 to 2024). Amyotrophic lateral sclerosis (ALS) is a neurodegenerative disease characterized by progressive muscular paralysis reflecting degeneration of motor neurons in the primary motor cortex, corticospinal tracts, brainstem and spinal cord. "Finally, we demonstrate that the EphB1–ephrin-B1 pathway is disrupted in human stem cell derived astrocyte and mouse models of amyotrophic lateral sclerosis (ALS)." (PMID 29079839, 2017). "The analysis has shown that the ephrin-B1-mediated stimulation induces a protective and anti-inflammatory signature in astrocytes and can be regarded as “help-me” signal of neurons that failed in early amyotrophic lateral sclerosis (ALS)." (PMID 38846640, 2024). "Here the authors identify a pathway via neuronal EphB1 that induces neuroprotective signalling in astrocytes through ephrin-B1 mediated STAT3 activation, which is impaired in models of amyotrophic lateral sclerosis." (PMID 29079839, 2017).
autoimmune disease (2 papers, 2022 to 2024). A disorder resulting from loss of function or tissue destruction of an organ or multiple organs, arising from humoral or cellular immune responses of the individual to their own tissue constituents. "The mother of the patient, who had the same CFNS phenotype and EFNB1 variant, was screened for autoimmune diseases and was also with autoimmune thyroiditis." (PMID 36558986, 2022).
Bladder Cancer (2 papers, 2020 to 2021). "The expression of ephrin-B1 is higher in bladder cancer tissues than normal urothelial tissue, suggesting that ephrin-B1 can be used as a biomarker of bladder cancer aggressiveness." (PMID 35126464, 2021).
breast tumor (2 papers, 2016). "The neurogenes APP and EFNB1 are upregulated in basal and HER2-enriched breast tumors meanwhile NGFR is upregulated only in basal-like breast tumors." (PMID 26673618, 2016).
cleft palate (2 papers, 2018 to 2020). Cleft palate is a fissure type embryopathy that affects the soft and hard palate to varying degrees. "In fact, several of the Shh target genes identified here in the cNCC, including Adamts9, Edn1, Dlg1, and Efnb1, are already implicated in cleft palate pathogenesis by existing mouse models." (PMID 29945554, 2018). "EPHRIN-B1 has strong expression in the anterior secondary palate mesenchyme, and loss of function of EFNB1 may result in cleft palate in both humans and mice." (PMID 32092051, 2020).
cognition disorders (2 papers, 2016 to 2019). "Dysfunction of EPHB2 and its ligand EFNB1 has been implicated in brain disorders, such as cognition disorders and depression." (PMID 31920518, 2019).
developmental delay (2 papers, 2019 to 2020). "It is the first time to report variants in EFNB1, NAA10, DHCR7, LAMA1 and NFIX in Chinese intellectual disability/developmental delay patients and first report about variants in NAA10 and LAMA1 in affected individuals of Asian ancestry." (PMID 31088393, 2019). "Unlike previous reports, we present a female infant with a de novo EFNB1 missense mutation that was demonstrated in clinical diagnosis as global developmental delay (GDD) and brain anomaly without frontonasal dysplasia or other malformation." (PMID 32984200, 2020).
experimental autoimmune encephalomyelitis (2 papers, 2021 to 2024). An autoimmune demyelinating disease of the central nervous system that is produced experimentally in animals by the injection of homogenized brain or spinal cord in Freund's adjuvant. "In experimental autoimmune encephalomyelitis and multiple sclerosis, the expression of EFNB1 and EFNB2 was found to be related to the migration of T cells." (PMID 35126464, 2021).
head and neck squamous cell carcinoma (2 papers, 2020 to 2021). A squamous cell carcinoma that arises from any of the following anatomic sites: lip and oral cavity, nasal cavity, paranasal sinuses, pharynx, larynx, and salivary glands. "Indeed, when dephosphorylated, ephrin B1 can bind to mitotic spindle microtubules, thus increasing the sensitivity to paclitaxel in head and neck squamous cell carcinoma and breast cancer cell lines." (PMID 33322542, 2020). "Expression and survival analyses based on the TCGA dataset of head and neck squamous cell carcinoma (HNSCC) samples indicated that the functional cooperation of TUBB4 and EFNB1 results in a poor prognosis." (PMID 35004310, 2021).
liver cancer (2 papers, 2024). An epithelial or non-epithelial malignant neoplasm that arises from the liver. "In vivo, it was found that ZIP4 and Ephrin-B1 expression were linearly correlated, and ZIP4 and Ephrin-B1 were independent risk factors for overall survival after liver cancer surgery." (PMID 39040931, 2024). "ZIP4 and Ephrin-B1 can be used as potential molecular targets for the treatment of liver cancer." (PMID 39040931, 2024). "In this study, we found that ZIP4 binds to Ephrin-B1 to inhibit the ubiquitination of Ephrin-B1, regulating the Wnt family member 5A (Wnt5A)/Jun N-terminal kinase (JNK)/ZEB1 signaling pathway and promoting EMT, thereby inducing invasion and metastasis of liver cancer cells." (PMID 39040931, 2024).
osteosarcoma (2 papers, 2022 to 2024). A usually aggressive malignant bone-forming mesenchymal neoplasm, predominantly affecting adolescents and young adults. "The most significant observation was that increased levels of ephrin-B1 were detected in osteosarcoma cells and blood vessels and were associated with local recurrence, metastatic disease and poorer clinical prognosis." (PMID 35563562, 2022). "For instance, ephrin-B1 enables invasive characteristics and resistance against chemotherapy of osteosarcoma cells and induces the migratory features of ERMS cells." (PMID 35563562, 2022). "The second mRNA profile was composed of ephrin-A3, ephrin-A5, and ephrin-B1 in a subset of osteosarcoma patients with possibly worse prognosis." (PMID 35563562, 2022). "In vitro, the mRNA expression levels of Hes1 from the Notch pathway and ephrin-B1 from the EPH/ephrin axis were found to be both elevated in 143B highly metastatic human osteosarcoma cells." (PMID 35563562, 2022). "In addition, ephrin-B1 levels were found de novo increased in primary osteosarcoma tumors but were significantly downregulated in metastatic osteosarcoma of the lungs." (PMID 35563562, 2022). "Eventually, specific anti-ephrin-B1 agents represent potential drug candidates that could eliminate the expansion and metastatic burden of osteosarcoma as well as counter the cells’ chemoresistance toward existing chemotherapeutic regiments." (PMID 35563562, 2022).
ovarian carcinoma (2 papers, 2006 to 2020). A malignant neoplasm originating from the surface ovarian epithelium. "Initially, the expression of 20 different Eph and ephrin genes (EphA1-A8, EphB1-4 and 6, ephrin A1-5 and ephrin B1-2) were screened by quantitative real time reverse transcriptase polymerase chain reaction (Q-PCR) on two normal ovaries and ten ovarian cancer specimens." (PMID 16737551, 2006). "This study showed that the most expressed genes in ovarian carcinomas were PAX8 (paired box gene 8), EFNB1 (ephrin-B1) and mesothelin." (PMID 33121141, 2020).
type 1 diabetes mellitus (2 papers, 2022 to 2024). A chronic condition characterized by minimal or absent production of insulin by the pancreas. "EFNB1 and RBBP4 enriched in the same items, such as type I diabetes mellitus, systemic lupus erythematosus, hematopoietic cell lineage, etc.." (PMID 39521940, 2024).
abdominal aortic aneurysm (1 paper, 2012). Enlargement and ballooning of the vessel that supplies arterial blood to the abdomen, pelvis and legs. "We examined the expression of ephrin-B1 and its cognate receptor EphB2, key regulators of angiogenesis and embryogenesis, in human abdominal aortic aneurysm (AAA) and analyzed their functional roles in cell migration." (PMID 22830028, 2012).
Anxiety (1 paper, 2024). Intense feelings of nervousness, tension, or panic often arise in response to interpersonal stresses. "Astrocyte-specific deletion of ephrin-B1 also enhances anxiety-like behaviors in the OF test, and juvenile P45–P50 ephrin-B1 KO mice also exhibit impaired sociability in the three-chamber test similar to P28 mice as previously reported." (PMID 39327008, 2024). "Together, the data suggest that impaired inhibition following the deletion of astrocytic ephrin-B1 is most likely responsible for increased susceptibility, duration, and severity of PTZ-induced seizures, as well as exacerbated repetitive and anxiety-like behaviors." (PMID 39327008, 2024).
Autoimmune Thyroiditis (1 paper, 2022). "This is the first report describing the association of CFNS with T1DM and autoimmune thyroiditis in patients with EFNB1 mutation." (PMID 36558986, 2022).
brain cancer (1 paper, 2022). A primary or metastatic malignant neoplasm affecting the brain. "EFNB1 expression is high in cancer cells and is potentially associated with tumorigenesis of gastric, ovarian, and brain cancer." (PMID 35565468, 2022).
colon carcinoma (1 paper, 2010). "This response was strongest for ephrin-B1 +EphB2 and ephrin-B1 + EphB3 with the response from ephrin-B1 and EphB4 only producing minor modifications in cell distribution and compartmentalization in the DLD1 colorectal adenocarcinoma and Co115 colon carcinoma cells lines used in that study." (PMID 20624275, 2010).
colorectal cancer (1 paper, 2022). A primary or metastatic malignant neoplasm that affects the colon or rectum. "Previous studies have demonstrated that colorectal cancer development and progression were suppressed by the repulsive interactions between ephrin-B1-positive normal epithelial cells and EphB-positive tumour cells." (PMID 35949596, 2022). "Finally, our investigations focused on EphB2 and ephrin-B1 expression in colorectal cancer; however, other ephrins, including Eph-B3 and Eph-B4, have also been implicated in colorectal carcinogenesis." (PMID 35949596, 2022).
demyelinating disease (1 paper, 2024). A broad group of disorders that affect the myelin sheaths that cover the neurons. "Future studies can address whether impaired ephrin-B1 expression in astrocytes is associated with demyelinating diseases such as MS and explore whether astrocytic ephrin-B1 may be useful as a therapeutic target to promote remyelination and oligodendrocyte survival in demyelinating diseases." (PMID 39437409, 2024).
depression (1 paper, 2019). "Given several key proteins within the pathway, such as Ephrin-B1 (EFNB1) and EPHB2, Ephrin receptor signaling may participate in inflammation-associated depression." (PMID 31920518, 2019).
diabetic retinopathy (1 paper, 2024). "In conclusion, a reduction in ephrin B1 in the diabetic retina may offer a new therapeutic modality for diabetic retinopathy." (PMID 38501146, 2024). "Future work can explore ephrin B1 in REC or other relevant cell types in diabetic retinopathy." (PMID 38501146, 2024).